IL2 (interleukin 2)
Diseases named in the same sentence as IL2 in open-access papers (continued):
Sharing a sentence is not in itself a finding about the gene and the disease.
glioma (continued). "They observed the strong reactivity of T cells using IL-2/IL-15/IL-2, given by the production of IFN-γ in the blood of patients with grade III glioma compared to patients with grade II glioma." (PMID 37759505, 2023). "GD2-CAR/NFATsyn-IL-12 T-cells readily killed GD2+ patient-derived glioma spheroids and secreted IL-12, TNF-α, IFN-γ, Il-2, perforin, and granzyme B upon coculture with GD2+ glioma cells." (PMID 38136398, 2023). "Triptolide-induced downregulation of glioma PD-L1 increased IFN-γ and IL-2 and reversed glioma-induced inhibition of CD4+ helper T cells." (PMID 36700235, 2022). "Cytokine mediated gene therapy involves tumor-selective gene transfer and in situ expression of various cytokine genes such as IL2, IL4, IL12, and IFNβ/γ which can induce robust immune responses to glioma cells." (PMID 33790740, 2021). "Ganoderma lucidum polysaccharides (GL‐PS) increased the concentration of serum IL‐2, TNF‐α and IFN‐γ and enhanced the cytotoxic activity of natural killer cells and T cells, inhibited glioma growth and prolonged the survival of rats." (PMID 34302428, 2021). "Combining the results obtained by silencing or over-expressing NFATc3, this study indicates that this member is involved in RCAN1-4, COX-2, TNF-α, IL-2, GM-CSF and CXCR-3 gene regulation in U251 glioma cells." (PMID 31249342, 2019). "Once NK cells are activated by various means including IL-2, IL-15, or PHA, they can overcome immune escape of glioma, such as HLA class I molecules, by overwhelming the activating signals." (PMID 28203118, 2017). "When combined with systemic IL-2 administration, it has been show that ACT effectively suppressed tumor growth in glioma-bearing rats." (PMID 23667419, 2013). "IL-2 and IFN-γ transduced rat RG2 (also known as D74) glioma cells, when injected into the brains of naïve rats, resulted in premature death of the rats due to changes in the vasculature of the brain." (PMID 21437175, 2010). "qRT-PCR assay demonstrated the upregulation of TNF-α, IL-2, IL-3, and IL-4 expression, whereas the downregulation of IL-12 expression in HK2-knockdown glioma cells, suggesting that HK2 is essential for glioma development through regulating immune infiltration." (PMID 35982398, 2022). "In C6 glioma cells, the chaperone activity of HSPB1 contributed to the production of the pro-inflammatory cytokine, IL-6, whereas T cells from HSPB1−/− mice exhibited reduced secretion of TNF and IL-2." (PMID 33423680, 2021). "It has been shown that by means of tumour-specific tropism of MSCs can be transduced to deliver anticancer agents such as interleukins (IL-2, IL-7, IL-18, and IL-12), TRAIL, and interferon (IFN-β and IFN-γ) directly to glioma sites to kill tumour cells or to regulate immune responses." (PMID 32981013, 2020). "We hypothesized that DC vaccination would activate and expand glioma-specific T cells whose recall response to gamma chain survival cytokines and/or TH1-type cytokines, such as interleukin 2 (IL-2) and interferon gamma (IFN-γ), would be enhanced." (PMID 24883189, 2014). "The underlying principle of cytokine mediated gene therapy involves tumor-selective gene transfer and in situ expression of various cytokine genes such as IL-2, −4, −12, and interferon (IFN)-β, −γ which can induce robust immune responses restricted to antigens specific to glioma cells." (PMID 26056588, 2014). "An analog of thalidomide, CC-5103 increases the secretion of critical cytokines of the tumor microenvironment, including IL-2, IFN-γ, TNF-α, and IL-10, and is currently being evaluated in clinical trials for the treatment of recurrent or refractory pediatric central nervous system tumors." (PMID 23717811, 2013). "However in our study, CD4+ CAR-T cells did not secrete enhanced levels of IL-2 upon exposure to glioma cells and failed to improve the therapeutic efficacy of CAR-NK cells." (PMID 40376677, 2025).
glioma (continued). "EGFR BATs infusions induced increases in glioma specific anti-tumor cytotoxicity by peripheral blood mononuclear cells (p < 0.03) and NK cell activity (p < 0.002) ex vivo, and increased serum concentrations of IFN-γ (p < 0.03), IL-2 (p < 0.007), and GM-CSF (p < 0.009)." (PMID 38263486, 2024). "Therefore, to further confirm our hypothesis, we next examined the expression of several key inflammatories and immune modulators, including TNF-α, IL-2, IL-3, IL-4, and IL-12, in HK2-silenced T98 and GBM1 glioma cells." (PMID 35982398, 2022). "PD-L1 expressed by glioma, in addition to increasing the number of T-reg cells, inhibits the functions of T lymphocytes and induces apoptosis of tumor-specific CD4+ and CD8+ T lymphocytes by decreasing the production of cytokines such as Inter-leukin-2 (IL-2) and interleukin-10 (IL-10)." (PMID 36555334, 2022). "Compared with the free SR717 and PBS groups, IL-2 levels in the SR717@RGE-HFn NP treatment group were increased by 4.96- and 6.97-fold, respectively, suggesting that SR717 substantially improved the adaptive T cell response within the glioma TME via the STING pathway when delivered by RGE-HFn NPs." (PMID 35386310, 2022). "The results indicated that DEGs are enriched in immune-related biological processes, including IL2/STAT5, IL6/JAK/STAT3, and Interferon-γ response signaling and the two categories identified by consensus clustering are correlated with immune infiltration of glioma." (PMID 33123464, 2020). "We reported previously previously that a cytokine cocktail comprising IL-2, IL-15 and IL-21 selectively increases the population of central/effector memory tumor-reactive tumor-infiltrating lymphocytes (TIL) from pancreatic cancer as well as TIL from WHO grade 4 glioma after ex vivo expansion." (PMID 29854291, 2018). "On the other hand, a clinical trial in phase I/II has been finished for EGFRvIII-positive glioma, which consists of a non-myeloablative lymphodepleting preparative regimen of cyclophosphamide and fludarabine in combination with the EGFRvIII-CAR-T cells and aldesleukin (IL-2) (NCT01454596)." (PMID 34769211, 2021).
Obesity (73 papers, 2010 to 2025). Accumulation of substantial excess body fat. "IR can instigate an upsurge of inflammatory cytokines associated with obesity, including IL-1β, IL-2, IL-4, IL-5, IL-6, IL-8, tumor necrosis factor-α, and interferon, which have been robustly linked to the development of PAH." (PMID 38702735, 2024). "The inflammation caused by insulin resistance can be identified by the increasing level of the serums TNF-α, IL-2, and IL-6 in the M group, indicating the inflammatory response is caused by obesity." (PMID 37569125, 2023). "In obesity, the expression of the AT IL-2 gene and protein was elevated, and it was highly associated with indicators of inflammation, metabolism, and insulin resistance." (PMID 37237937, 2023). "We were able to demonstrate that obesity is associated with up-regulation of several pro-inflammatory cytokines, including IL-1ra, IL-2, IL-16, MCP-1, MIG, RANTES, C5a and sICAM-1." (PMID 22748184, 2012). "As a result, it implies that obesity may be a prediction of AT malfunction, which is linked to monocyte and macrophage invasion and the production of IL-2 by active T cells." (PMID 37237937, 2023). "Besides, a hybrid cytokine IL233 with the activities of both IL-2 and IL-33 protects mice from obesity-linked diabetic nephropathy with a more significant accumulation of Tregs, ILC2s, M2 macrophages, and eosinophils in VAT." (PMID 35574038, 2022). "These inflammatory cells likely contribute to the pathology of obesity-induced lymphatic dysfunction since inhibition of inflammatory reactions with topical IL-2 inhibitors or genetic deficiency of CD4+ T cells decreased the severity of lymphatic injury in obese animals." (PMID 32268536, 2020). "Our study supports the notion that biologically relevant changes in the IL-8 and IL-12 gene expression in AT might be linked with the increased IL-2 expression in obesity settings." (PMID 33004937, 2020). "Furthermore, the role of IL-2 a cytokine pivotal for T-cell regulation and immune tolerance—remains underexplored in schizophrenia-related obesity, despite evidence linking IL-2 deficiency to impaired lipid metabolism and adipocyte dysfunction in preclinical models." (PMID 40791199, 2025). "Thus, it implies that obesity could be a predictor of AT dysfunction, associated with infiltration of monocytes/macrophages and activated T-cells as the source of IL-2." (PMID 33004937, 2020). "In patients with obesity complicated by T2D, their functional capacity appears impaired, with reduced secretion of IL-2 and IL-4, which are essential for the protective, anti-inflammatory function of these cells (particularly iNKT) in adipose tissue." (PMID 41425544, 2025). "Down-regulation of IL-2 in obesity has been shown also in studying human preadipocytes and adipocytes." (PMID 40426748, 2025). "For instance, interleukin (IL)-2 is an important anti-inflammatory cytokine that also contributes to immune changes during inflammation and obesity." (PMID 38255781, 2024). "Circulating MAITs in obesity and metabolic disease are characterized by increased IL2, granzyme B, IL17, IFNγ, and TNFα, and less IL10 compared to healthy controls." (PMID 38674935, 2024). "Obesity, as a chronic inflammatory condition, has been well reported to maintain increased systemic interleukin (IL)-2, IL-4, IL-6, TNFα, IFNγ, and GM-CSF levels in a manner modulated by physical activity." (PMID 36143948, 2022). "Conversely, their expansion using the IL-2/anti-IL-2 antibody complex in HFD-fed mice improved obesity-induced insulin resistance." (PMID 36364954, 2022). "Obesity also affected cellular responses: PBMCs of the obese vaccinees had elevated interleukin 2 and interferon γ levels upon antigen stimulation, indicating a leptin-dependent proinflammatory TH1 polarization." (PMID 32528467, 2020).
Obesity (continued). "Consistent with IL-2 mRNA data, the immunohistochemistry (IHC) data revealed that IL-2 protein levels were significantly (P = 0.0032 and P = 0.0001, respectively) higher in individuals with obesity as compared to lean controls." (PMID 33004937, 2020). "In conclusion, our data show that AT IL-2 gene/protein expression was increased in obesity and it positively correlated with metabolic and inflammatory signatures, along with insulin resistance markers." (PMID 33004937, 2020). "Development of obesity in mice was correlated with a change in cytokine profile with decreased IL-2 and increased IFN-γ and IL-4." (PMID 31947953, 2020). "In humans, plasma levels of IL-2 and their relationship with BMI and obesity status remain controversial." (PMID 33004937, 2020). "The activity of IDO is stimulated by proinflammatory cytokines, which are elevated in obesity: interleukin-2 (IL-2), interferon-γ (IFN-γ), and tumor necrosis factor-alpha (TNF-α)." (PMID 31906073, 2019). "Obesity for donor is also related to CD4+ T cell–mediated aGVHD of recipients by controlling the differentiation of CD4+IL-2+, CD4+IFN-γ+ and CD4+TNF-α+ and Th17 cells." (PMID 29088831, 2017). "Obesity induced adipose tissue cytokine expressions, the most highly upregulated cytokines being IL-1ra, IL-2, IL-16, MCP-1, MIG, RANTES, C5a, sICAM-1 and TIMP-1." (PMID 22748184, 2012). "Furthermore, obesity has been implicated as a factor in liver diseases and HCC which correlates with our findings of higher secretion of IL-6, IL-2, and MCP-1 in PLWH who are obese." (PMID 41219858, 2025). "Our snRNAseq data showed that obesity modulated expression of genes in microglia that are involved in cell–cell adhesion, cell signaling, and regulation of inflammation and immune response (31 DEGs), including chemokine signaling and IL-2 signaling." (PMID 39456952, 2024). "In addition, obesity was linked to a higher IFN-γ response to SARS-CoV-2 S1, a higher CD8 + T cells proliferation to S1, S2, ORF 7 and 8, and an increased CD8 IL-2 response to spike." (PMID 38642547, 2024). "Many cytokines, particularly Th1-derived cytokines such as TNF-α, IFN-γ, IL-6, and IL-2, are increased when obesity is present, resulting in chronic low-grade inflammation that may predispose individuals to hypersensitive reactions." (PMID 36614274, 2023). "IL-2 is produced by the activated T cells that enter adipose tissue in obesity." (PMID 37237937, 2023). "Indeed, individuals with obesity and T2D had a lower production of IL-2 (proliferation marker), IL-6 and TNF-α by peripheral blood mononuclear cells (PBMCs) stimulated with phytohaemagglutinin, a T-cell mitogen." (PMID 35187037, 2022). "Moreover, another pleiotropic cytokine, IL-2, has been reported to contribute to immune alterations during inflammation and obesity." (PMID 35328382, 2022). "IL-2 from ILC2s in the small intestine may thus be critical to the induction of obesity and insulin resistance." (PMID 35574038, 2022). "It is well known that a decrease of NFATC2 expression is associated with a reduction of the expression of cytokines in T cells, in particular IL-2, IL-3, IL-4 and TNF-alpha; the latter, in particular, is a pro-inflammatory cytokine associated with obesity and insulin resistance." (PMID 35159548, 2022). "Obesity is considered a significant contributor to inflammatory cytokine production, and it was reported as a risk factor for both CRS and neurotoxicity in patients treated with IL-2." (PMID 34771451, 2021). "IL-15 and IL-2 have several similar functions and are highly expressed in obesity." (PMID 33526854, 2021). "However, IL-2 expression and its relationship with other significant markers of metabolic inflammation in obesity is not well understood." (PMID 33004937, 2020). "In the context of obesity, our results imply that the co-expression of IL-2 with the studied inflammatory cytokines/chemokines could contribute to enhancing metabolic inflammation and insulin resistance in the AT." (PMID 33004937, 2020).
Obesity (continued). "Vγ9Vδ2 T cell dysfunction in obesity can be reversed with the addition of IL-2 signaling during influenza infection, suggesting that there may be a lack, or suppression, of appropriate cytokine reception in the obese environment." (PMID 25785862, 2015). "With IL-2 levels limiting in obesity, we investigated whether Vγ9Vδ2 T cell antiviral functional responses could be restored by the addition of this cytokine." (PMID 25785862, 2015). "However, with the obesity presence in the paediatric population, IL-2-mediated inflammation might be even reduced." (PMID 40426748, 2025). "Visceral and subcutaneous LECs displayed an obesity-associated upregulation of the RAGE pathway, integrins and ECM–receptor interactions, while a downregulation in the brain-derived neurotrophic factor (BDNF), interleukin-5 (IL-5), IL-2 and AP1 networks was observed." (PMID 36400935, 2022). "Interplay between hormones and cytokines may also be important as TNFα, which reduces insulin sensitivity and has been shown to be overexpressed in people with obesity, is partially mediated by leptin in addition to IL-2, and IL-6 cytokines that increase T-cell expansion and liver disorders." (PMID 36143948, 2022). "Inflammatory markers, including CD16, CD11c, CCR2, CCR5, TNF-α, IL-1β, IL-2, IL-12, CCL8, CCL19, and CXCL9, were positively correlated with IL-23 in the AT-compartment in the obesity context." (PMID 41158638, 2025). "In obesity, the hippocampal level of CREB and the pro-inflammatory cytokine, such as IL-2, is suppressed." (PMID 37237937, 2023). "Certain inflammatory enzymes like interleukin-2 (IL-2), interleukin-10 (IL-10), interferon-γ (IFN-γ), and interleukin 1-α (IL1-α) were found to differ between participants with obesity and with normal BMI." (PMID 36612361, 2022). "So far, both experimental and clinical studies have shown that CD8+ lymphocytes can increase the production of pro-inflammatory factors, e.g., TNF-α, interleukin 2 (IL-2), IFN-γ and RANTES chemokines, contributing to inflammation in the course of obesity." (PMID 34564433, 2021). "While obesity alone increases pro-inflammatory IL-1β, TNFα, MCP1, and keratinocyte-derived chemokine, obesity decreased the extent to which TNBS-colitis increased IL-2 and IFN-γ in mesenteric adipose and intestinal tissues." (PMID 33603741, 2020). "Statistically, the concentrations of GROα, IL-2, IL-4, IL-6, IL-17A, IL-22, IL-23, and MCP-3 were significantly higher in males with obesity compared to the females with obesity, while the concentrations of IL-5, IL-10, IL-18, MCP-1, and MIP2α trended higher (p ≤ 0.1)." (PMID 41488663, 2025). "Sixth, This study only examined the relationship between IL-6, TNF-α, and IL-2 levels and psychiatric symptoms and obesity, without testing other factors, particularly C-reactive protein (CRP) and interleukin-10 (IL-10)." (PMID 40791199, 2025). "Likewise, in females with obesity, vaccinated mice had significantly lower levels of eotaxin, GM-CSF, GRO-α, IL-1β, IL-2, IL-5, IL-6, IL-12p70, IL-17A, IL-18, IP-10, MCP-1, MCP-3, MIP-1α, MIP-1β, MIP-2α, and TNF-α compared to unvaccinated controls." (PMID 41488663, 2025). "Other studies report an elevated expression of the Th1 transcription factor and heightened production of cytokines IL-2 and INF-γ in women with obesity and GDM, suggesting that the inflammatory state in this condition results from an imbalance in the Th1/Th2/Treg ratio." (PMID 40724491, 2025). "Moreover, obesity induced the activation of IFN, TNFα, IL-2 and IL-6 signaling in the aEC population." (PMID 36400935, 2022). "According to our results, IL-2 might be down-regulated in children with obesity with negative correlations with several adiposity measures and associated laboratory results affecting low-grade inflammation in early stages of obesity." (PMID 40426748, 2025).
Obesity (continued). "Moreover, individuals with obesity and T2D had a higher proportion of immune cells expressing activation markers such as CD80, and T cells expressing CD278, which play an important role in IL-2 production and T cell proliferation." (PMID 35782930, 2022). "Notably, significant elevations in IL-2 expression in the AT together with that of other inflammatory mediators (IL-8, IL-12A, CCL5, CCL19, CCR2 and CCR5 and TLRs) in obesity suggests that these factors may contribute cooperatively for insulin resistance induction in this population." (PMID 33004937, 2020). "Consistent with our hypothesis, certain inflammatory markers, as IL-2, IL-10, IFN-γ and IL1-α, were found to differ between AN and HCs, as well as between AN and participants with obesity with or without BED." (PMID 31450770, 2019).